IL6 (interleukin 6)
Diseases named in the same sentence as IL6 in open-access papers (continued):
Sharing a sentence is not in itself a finding about the gene and the disease.
infection (continued). "We observed that the production of pro-inflammation TNF-α and IL-6 and the immunoregulatory IFN-β, MCP-1 and KC were significantly decreased later in infection (at 6 or 8 dpi) compared with non-treated mice, indicating the accelerated recovery from the immunity situation resulting from infection." (PMID 28235408, 2017). "In humans, following H7N9 infection, there is excessive expression of pro-inflammatory factors CCL2, IL-6, IL-8, IFNα, interferon-γ, IP-10, MIG and macrophage inflammatory protein-1β, which has been shown to contribute to fatal disease outcomes in mouse models of infection." (PMID 28435679, 2017). "The simultaneous decrease of IL-6 levels could be a marker for the lack of C. trachomatis EBs infection of host cells due to the presence of bLf." (PMID 28914813, 2017). "Furthermore, MC-derived IL-6 and TNF-α in this phase of infection may contribute to granuloma maintenance." (PMID 29089945, 2017). "Therefore, it seems the typical presentation of human patients infected with either virus includes high levels of CXCL10, CCL2, IL-6, and CXCL8 in the plasma, peripheral blood leukopenia, and lung neutrophilia, and this is also similar to experimental infection of laboratory animal models." (PMID 28553293, 2017). "The results indicate that the expression levels of IFN-γ and IL-2, but not IL-6 and IL-4, were elevated in the Tris-HCl control or adjuvant vaccinated mouse splenocytes and had the potential for proliferation after infection of Babesia parasites or BMSA stimulation." (PMID 29312230, 2017). "Although the mean IL-6 levels in asthmatic mice challenged with A(H1N1)pdm09 were low (118.9 pg/mL) at 2 days post-infection, the levels were markedly increased (to 1578.2 pg/mL) at 3 days post-infection, and the levels in all groups remained high at 7 days post-infection." (PMID 28831046, 2017). "In particular, the pronounced degree of adaptation observed for Il1b and Il6 in vivo suggested that additional negative feedback constraints may enforce adaptive recovery to infection or insult in the CNS." (PMID 28855862, 2017). "In EBOV-infected patients, fatal infection was associated with high levels of IL-10 and IL-1RA, modest levels of TNF-α and IL-6, and non-detectable levels of IL-1β, MIP-1α, and MIP-1β, while survivors were characterized by high levels of TNF-α, IL-1β, and IL-6 in plasma." (PMID 28861075, 2017). "Importantly, however, this effect seemed independent of the outcome of the infection, as IL-6 was not necessary for control or clearance of RSV." (PMID 28953978, 2017). "Five days post infection with T. spiralis, chitosan appeared to influence the levels of myeloperoxidase (MPO) and cytokines in mice: higher levels of MPO, MCP-1, TNF-α, IL-12p70, IL-6, IL-10 and TGF-β were found in infected mice treated with chitosan compared to those who were not." (PMID 29156562, 2017). "Importantly here we found that IL-6 mediated immune-regulation occurs via the induction of IL-27 in the airways after infection, without any effect on peak viral loads or viral clearance." (PMID 28953978, 2017). "THP-1 cells were, therefore, stimulated with 1 μg/ml LPS, a concentration mimicking an infection from Gram-negative bacteria, in the presence or absence of 100 μg/ml bLf, and production of IL-6 and IL-1β as well as expression of Fpn, TfR1, Ftn, and Cp-GPI was assessed." (PMID 28663751, 2017). "Under high glucose conditions (50 mmol/L), siTIPE2 infection exacerbated the increased TNF-α and IL-6 concentrations in differentiated THP-1 cells, and Ad-TIPE2 infection reversed the increased TNF-α concentration, while Ad-TIPE2 infection had no obvious effect on the increased IL-6 release." (PMID 28626770, 2017). "Additionally, a downmodulation of IL-6 in villous explants after infection by T. gondii and treated or not with enrofloxacin, toltrazuril, or combination of sulfadiazine plus pyrimethamine was observed in the present study." (PMID 28798905, 2017).
infection (continued). "Considering only our results of inflammatory profile in macrophages, strains such as CRL72, CRL1446, CRL352, CRL431, and CRL117 with a medium inflammatory profile could provide protection against the early stage of infection via Th1 with TNF-α and IL-6 production." (PMID 28348560, 2017). "Notably, in the absence of infection, pregnant uninfected mice overexpressed lung neutrophil-recruiting chemokines (KC, 1.37 times higher) and cytokines (IL-1β, IL-6 and G-CSF; 1.64-, 7.6- and 3-times higher respectively) relative to non-pregnant controls." (PMID 29176767, 2017). "At 3 dpi, the levels of IFN-γ, IL-6, IL-10, MCP-1, and TNF-α in BALB/c mice infected with MA/12 were considerably higher than in animals inoculated with PH/13 or BR/08; however, only the IL-10 elevation was significant (P < 0.05) relative to that observed with PH/13 infection." (PMID 28779075, 2017). "Consistently, mRNA transcripts of the IL-12 receptor and numerous cytokines, including MCP-1, IP-10, IL-6, IFN-β and GM-CSF, were significantly lower in CD8+ T cells enriched from the blood as compared to non-CD8+ cells of stat1loxP/loxP/Vav-cre mice at day 3 post infection." (PMID 28290449, 2017). "No changes in IL-6 secretion were observed with M(LPS + IFN-γ) after the infection." (PMID 29250063, 2017). "Since IL-6 and MCP-1 were reported to be able to alter tight junction expression, this finding implies that AG1478 might specifically protect the brain from cytokine/chemokine-mediated BBB disruption in early infection." (PMID 27756321, 2016). "Moreover, increased levels of major pro-inflammatory cytokines IL-6, TNF-α and chemokine MCP-1, have been demonstrated from the murine lung epithelial cell line, primary lung epithelial cells and an inhalational murine infection model." (PMID 27529172, 2016). "Elevated levels of IL‐6 are associated with early and late AMD and are significantly related to smoking, higher body mass index, and “inflammaging”, the low‐grade, chronic, systemic sterile inflammation in aging, in the absence of infection." (PMID 27861126, 2016). "The levels of inflammatory cytokines and chemokines, i.e., IL-6, TNF-α, CCL3/MIP-1α, CXCL1/KC, and CXCL10/IP-10, which have been reported to contribute to lung pathology, also decreased in BALF from Mint3−/− mice compared to those from WT mice on day 4 after infection." (PMID 27883071, 2016). "As hypothesized, the levels of inflammatory mediators (IL-6, CCL2, CCL3, CXCL1, CXCL10 and IFNα as expected) were lower in the blood and the spleen of Ifnar1-/- mice compared to WT counterparts at all times post-infection, except for IFNγ." (PMID 27792766, 2016). "However, significant IL6-dependent STAT1 Y701 phosphorylation was only observed with the wild-type and revertant but not the mutant virus at both early (24 h) and late times (72 h) post infection." (PMID 27387064, 2016). "Therefore, it is reasonable to postulate a more pervasive mechanism in DENV-ADE infection, which does not rely on the suppression of IFNα/β or increased IL-10/IL-6." (PMID 26923481, 2016). "The expression of IL-6 and KC cytokines appeared to track with disease progression, nonsequentially with viral load, but the differences among oseltamivir treated and untreated groups were not significant at these infection dose levels except for the IL-6 cytokine in the prophylactic group." (PMID 27110056, 2016). "Moreover, and also in line with the results obtained in BEAS-2B cells, S. pneumoniae did not further increase IL-6 release after RSV-infection in pBECs." (PMID 27259950, 2016). "However, the IL-6, TNF-α, and IL-12p70 levels induced by either ΔsspA-1 or ΔvirD4–89K were markedly lower than those induced by the wild-type strain, particularly at 8 h after infection." (PMID 27270879, 2016).
infection (continued). "By correlating the pain thresholds with the cytokines levels time courses as well as the treatment period, it was concluded that IL-1β and IL-6 do not play a direct role and that other mediators are involved in L. major induced hyperalgesia at least during later stages of the infection." (PMID 26913003, 2016). "Thus, overall, the addition of IL-2 and IL-6 to murine memory CD8+ T cells can boost their GrB expression, which could aid in viral clearance during an infection." (PMID 27322555, 2016). "Independent of C. jejuni-infection and feeding strategy, C. jejuni-free layers showed significant higher IL-6 mRNA expression levels only at 1 dpi, as well as IL-8 mRNA expression levels at both 1 and 7 dpi compared to C. jejuni-free broilers, indicating a breed effect (p < 0.05)." (PMID 27843492, 2016). "Previous studies have shown that curcumin inhibits NFκB pathways and production of IL-6, IL-8 and TNF-α following N. gonorrhoeae stimulation of the HeLa cervical epithelial cell line, and completely abolishes the adherence of bacteria to cells in late infection." (PMID 25856395, 2015). "Interestingly, IL-6 levels are also upregulated in amniotic fluid and uterine tissues in term labor without any sign of infection." (PMID 25961579, 2015). "In all controls without infection, IL-6 concentrations were below the calibration range." (PMID 26225421, 2015). "These facts could also explain why only serum concentrations of IL-6 and IL-8 were significantly higher in the patients with non-IE infections when this group was compared to the healthy controls." (PMID 26225421, 2015). "Neither oseltamivir nor TVB024 significantly reduced infection-induced IL-6 production." (PMID 25934861, 2015). "Indeed, it has been shown that inactivated CVB4 can stimulate the production of IL-6, TNFα and IL-12 by monocytes, which suggests that a replicative infection of monocytes/macrophages by the virus is not mandatory for inducing inflammation." (PMID 26610550, 2015). "However, studies using IL-6 knockout mice demonstrated that a complete lack of IL-6 strongly compromised mice in several models of infection leading to increased tissue damage and the accumulation of viable bacteria." (PMID 26126119, 2015). "However, few studies evaluated the role of PCT and IL6 in predicting cancer and its progression independent of co-existing infection." (PMID 26148092, 2015). "Infection at delivery, but not earlier in pregnancy, was associated with significantly higher TLR3-mediated IL-6 and IL-10 responses in the first 3 months of life, and with significantly higher TLR3-/TLR7/8-/TLR9-mediated TNF-α and TLR9-mediated IL-10 responses at 6 or 12 months of age." (PMID 26580401, 2015). "Hence, the increased expression of IL-6, IL-1β and CCL2 at later stages of infection may act to promote osteoclastogenesis." (PMID 25407789, 2014). "We observed that a number of NF-κB inducible genes were significantly elevated at 4 weeks post-infection (but not at 2 weeks) by qRT-PCR in B6 miR-146a−/− joints, compared to WT, including cytokines IL-1β and IL-6, as well as neutrophil chemokines Cxcl1 and Cxcl2." (PMID 24967703, 2014). "Additionally, the deficiency of pandemic-like H5N1 whole virus vaccines to induce secretion of inflammatory cytokines (i.e. IL-6, TNF-α, and IFN-α) was unexpected, since the infection of humans with live H5N1 viruses was reported to be associated with hypercytokinemia." (PMID 25072749, 2014). "IL-6 and TNF-α production upon Lae 303 and 327 infection was less than that observed for L. guyanensis, which might be attributable to the lower LRV load in the L. aethiopica strains and/or because of a higher parasite survival rate in the case of L. aethiopica." (PMID 24762979, 2014). "TLR9-/- AMs infection with the ΔPscf mutant induced both TNFα and IL-6 but failed to induce IL-1β." (PMID 24595157, 2014).
infection (continued). "We found that the levels of proinflammatory cytokines, including IL-6, MCP-1, IL-1β, TNF-α, and IFN-γ, increased immediately after infection and peaked on day 3 postviral infection, before returning to their baseline levels about 7–10 days after infection in both mouse strains." (PMID 24676272, 2014). "Furthermore, not only local, but even systemic immune responses were less pronounced upon ΔhtrA mutant infection as indicated by significant lower serum levels of pro-inflammatory cytokines such as TNF-α and IL-6 in ΔhtrA mutant as compared to WT strain infected mice." (PMID 24959425, 2014). "Therefore, the significantly higher production of IL-6 on day 5 might contribute to the significantly higher recruitment of CD4+ and CD8+ T cells in the control mice at day 9 after H9N2 infection." (PMID 24465940, 2014). "Significant up-regulation (p < 0.05) of LITAF, IL-6 and IL-8 was also detected in lung and spleen tissues from three-week-old chickens at 24 h of infection with H5N1-tyTR05 or H5N1-tyEng91 HPAI viruses (data not shown), along with abundance of virus matrix gene expression." (PMID 25431115, 2014). "S. aureus molecules such as peptidoglycan and lipoteichoic acid (LTA) are potential stimulators of cytokine production (e.g. TNF-α, IL-1β, IL-6, IL-4, IL-8, IFN-γ and IL-12), in response to infection but un-regulated cytokine production may contribute to S. aureus pathogenesis." (PMID 25398383, 2014). "IL-6, IL-1 and TNF-α are important cytokines in the immune response against Listeria, therefore their production by mast cells upon exposure to the bacteria may contribute to the immune defence against this infection." (PMID 23460827, 2013). "Here we show that IL-6 concentration was markedly lower in footpads of mycobacteriophage D29 treated mice at day 68 post-infection (day 35 after treatment) as compared to non-treated mice, confirming that footpad tissue damage is less severe in D29 phage treated footpads." (PMID 23638204, 2013). "To assess the expressions of inflammatory cytokines following infection with DM-C, we quantified the amount of representative proinflammatory cytokines, including tumor necrosis factor-alpha (TNF-α), interleukin-1β (IL-1β), and IL-6, in the bronchoalveolar lavage fluid (BALF) of infected mice." (PMID 24098364, 2013). "No changes in the expression of intestinal IL-1β and IL-6 were observed at day 2 post infection." (PMID 24340048, 2013). "Unlike CRP and IL-6, IL-8 showed a significant increase only in the infected neonates when compared to the non-infected and control neonates indicating that it is increased only in infection and not in inflammation." (PMID 23869218, 2013). "By contrast, at 7 days post infection, the levels of CCL2, CCL3, CXCL2, IFN-γ and the anti-inflammatory cytokine IL-10 were significantly lower in influenza A virus-infected Nox1−/y lung compared to WT control, whereas IL-β, IL-6, TNF-α, and GM-CSF were similar between the two strains of mice." (PMID 23577160, 2013). "Interestingly, contrary to the production of defensins, we observed that MSM induces high levels of IL-6 in the fibroblasts; therefore, the MSM infection produces a high pro-inflammatory environment that indirectly favors a rapid elimination of the mycobacteria." (PMID 25436879, 2013). "In this study, the lack of TNF-α, IL-6 and IL-12 induction on day 10 post-infection could result in an incomplete immune response against B. pseudomallei." (PMID 23951382, 2013). "Furthermore, uninfected mice treated with G-CSF demonstrated dampened responses to IL-2 and IL-6, indicating that neutrophil-mediated control of IL-2 induced pSTAT5 and IL-6 induced pSTAT1 responses are independent of infection." (PMID 23754944, 2013).
infection (continued). "In addition, blood samples were collected at 2, 6, 24 and 48 h post-infection to analyse the production of inflammatory cytokines such as TNF-α, IFN-γ, IL-6, keratinocyte chemoattractant (KC or CXCL-1, equivalent to human IL-8) and anti-inflammatory cytokine IL-10." (PMID 24107297, 2013). "In the later phase of infection, WT mice remained immunosuppressed lacking the ability to mount an effective immune response to bacterial invasion noted by the inability to produce proinflammatory genes such as IL-6 and IL-17 at 14 days PI." (PMID 23469071, 2013). "Data were available for meta-analysis for CRP for microbiologically or clinically documented infection; for PCT assessing microbiologically or clinically documented infection; and IL6 reporting microbiologically or clinically documented infection, and gram negative bacteremia." (PMID 22257704, 2012). "The concentrations of IL-6 and CCL5 were dependent on the dose of infectious virus and the concentration of these cytokines induced by NH1125 was greater than that of those induced by NH1067 when the multiplicity of infection of NH1067 used was as much as 10-fold higher than that of NH1125." (PMID 22962966, 2012). "Since cytokine production pattern is highly influenced by the presence of growth factors that are secreted by cells, we additionally measured IL-6 and IL-8 in noncumulative culture supernatants collected from day-1 to-3 infected cells as a function of time 1 to 4 days after infection." (PMID 22529524, 2012). "Among the three resistant strains, we find that the NOD/ShiLtJ and C57BL/6J strains have similar patterns: no deaths observed within five days post infection, low average kidney counts, moderate average peritoneal fluid counts, and high average levels of serum IL-6." (PMID 22690378, 2012). "On classification of the pathogens into three groups, there was a significant difference between the readings of the IL-6 among the patients who were infected with Gram-negative bacteria and those who had no infection as well as those who were infected by pathogens other than Gram-negative bacteria." (PMID 23724320, 2012). "Indeed, infection with the virulent strain also led to an increase in expression (1.5 to 2.3 fold) for most of the other pro-inflammatory mediators tested (CCL20, IL-6, IL-12p40, and IFN-γ) as well as to an upregulation (1.7 fold) of the antimicrobial LeukoP as compared to the UI control loops." (PMID 22675469, 2012). "The degree of placental IL-6 gene expression was not affected by fetal infection in BALB/c mice." (PMID 22952869, 2012). "Four provided data on IL6 and documented infection or gram negative bacteremia." (PMID 22257704, 2012). "While IL-17R KO animals predictably had significantly higher amounts of IL-17 in brain abscess homogenates, several other mediators were also elevated between 7 and 14 days after infection, including IL-1α, IL-1β, IL-6, CCL3 and CXCL1 (data not shown), as well as CXCL2 and CXCL9." (PMID 22704602, 2012). "In addition, infection of respiratory airway epithelial cells (AEC) with influenza virus triggers release of cytokines and chemokines (including IP-10, IFNβ, RANTES and IL-6) that promote the recruitment of blood-derived inflammatory cells, including neutrophils and monocytes." (PMID 22238612, 2012). "Humans infected with VN1203 viruses exhibit abnormally high levels of IL-6 in serum, and aberrant upregulation of IL-6 is observed in primary human alveolar and bronchial epithelial cells in response to VN1203 infection, relative to infection with a low pathogenicity H1N1 isolate." (PMID 22074594, 2011).